GRXCR1 (glutaredoxin and cysteine rich domain containing 1)
Description:
May play a role in actin filament architecture in developing stereocilia of sensory cells.
Synonyms: DFNB25; PPP1R88
Tractability: PROTAC: ubiquitination databases record sites on it.
Gene: Protein-coding gene on chromosome 4 (42,892,713 to 43,030,658, forward strand). Ensembl gene ENSG00000215203.
Subcellular location: Cell projection, stereocilium; Cell projection, microvillus; Cell projection, kinocilium
Pathways (Reactome):
Sensory Perception: Sensory processing of sound by inner hair cells of the cochlea; Sensory processing of sound by outer hair cells of the cochlea
Gene Ontology:
Molecular function: protein binding
Biological process: inner ear receptor cell development; inner ear receptor cell stereocilium organization; sensory perception of sound; vestibular receptor cell development
Cellular component: kinocilium; stereocilium; microvillus
Genetic constraint (gnomAD): Loss-of-function variants: 24 observed, 24.52 expected, observed/expected ratio (o/e) 0.98, 90% interval 0.71 to 1.38. The upper end of that interval is the gene's LOEUF score, 1.38, which puts it in group 5 of 6, group 1 being the genes least tolerant of losing a copy. Missense variants: 359 observed, 348.3 expected, observed/expected ratio (o/e) 1.03, 90% interval 0.94 to 1.12. Synonymous variants: 117 observed, 130.98 expected, observed/expected ratio (o/e) 0.89, 90% interval 0.77 to 1.04.
Gene-disease validity (ClinGen):
ClinGen rates the evidence that GRXCR1 causes each of these diseases.
nonsyndromic genetic hearing loss (autosomal recessive): Definitive. A disease characterized by hearing loss that is not part of a larger syndrome.
Homologues: Orthologues: chimpanzee GRXCR1 (99% identical), macaque GRXCR1 (98% identical), rabbit GRXCR1 (96% identical), guinea pig GRXCR1 (94% identical), dog GRXCR1 (94% identical), pig GRXCR1 (94% identical), mouse Grxcr1 (92% identical), rat Grxcr1 (92% identical), tropical clawed frog grxcr1 (80% identical), zebrafish grxcr1a (66% identical), Drosophila melanogaster CG12206 (32% identical), Drosophila melanogaster CG31559 (31% identical), and 2 more. Paralogues in human: GRXCR2 (28% identical), GLRX2 (10% identical).
Diseases named in the same sentence as GRXCR1 in open-access papers:
GRXCR1 is named in the same sentence as 4 diseases in open-access papers, as found by Europe PMC text mining. Sharing a sentence is not in itself a finding about the gene and the disease. The quoted sentences say what the papers report.
hearing loss (5 papers, 2014 to 2026). "Ironically, both ADGRV1 and GRXCR1 are associated with auditory hair development and mutations are linked to hearing loss." (PMID 29670642, 2018). "The results of gene expression analysis of each cochlear turn showed that 4 ADNSHL genes (Pou4f3, Slc17a8, Tmc1, and Crym) and 9 autosomal recessive non syndromic hearing loss genes (Otof, Strc, Ush1c, Pcdh15, Grxcr1, Dfnb59, Slc26a5, Lhfpl5, and Ptprq) were changed 2-fold or more." (PMID 24676347, 2014). "Mutations in human glutaredoxin domain-containing cysteine-rich protein 1 (GRXCR1) and its paralog GRXCR2 have been linked to hearing loss in humans." (PMID 34366792, 2021).
deafness (2 papers, 2016 to 2018). An inherited or acquired condition characterized by the complete loss of the ability to hear from one or both ears. "Grxcr1, a gene required for establishing normal stereocilia diameter during development, is mutated in the mouse pirouette strain, which exhibits profound deafness and vestibular dysfunction." (PMID 30157177, 2018). "Like many mouse deafness mutants, Grxcr1 mutants exhibit behavioral defects such as circling and head shaking that are typical of vestibular dysfunction." (PMID 30157177, 2018).
Usher syndrome (1 paper, 2022). A syndromic diseae characterized by the association of sensorineural deafness (usually congenital) with retinitis pigmentosa and progressive vision loss. "GRXCR1 is an enzyme that has been shown to remove glutathione groups from target proteins, and it has been suggested to destabilize the interaction between the Usher Syndrome proteins USH1C and USH1G in zebrafish." (PMID 35235570, 2022).
GRXCR1 also shares sentences with these, for which no sentence is quoted: Hearing impairment (1 paper).